TUT1 (terminal uridylyl transferase 1, U6 snRNA-specific)
Description:
Poly(A) polymerase that creates the 3'-poly(A) tail of specific pre-mRNAs. Localizes to nuclear speckles together with PIP5K1A and mediates polyadenylation of a select set of mRNAs, such as HMOX1. In addition to polyadenylation, it is also required for the 3'-end cleavage of pre-mRNAs: binds to the 3'UTR of targeted pre-mRNAs and promotes the recruitment and assembly of the CPSF complex on the 3'UTR of pre-mRNAs. In addition to adenylyltransferase activity, also has uridylyltransferase activity. However, the ATP ratio is higher than UTP in cells, suggesting that it functions primarily as a poly(A) polymerase. Acts as a specific terminal uridylyltransferase for U6 snRNA in vitro: responsible for a controlled elongation reaction that results in the restoration of the four 3'-terminal UMP-residues found in newly transcribed U6 snRNA. Not involved in replication-dependent histone mRNA degradation.
Synonyms: RBM21; FLJ22347; FLJ22267; FLJ21850; PAPD2; TUTase; TENT1; STARPAP; URLC6
Tractability: Small molecule: a structure with a bound ligand is known. PROTAC: ubiquitination databases record sites on it.
Gene: Protein-coding gene on chromosome 11 (62,575,045 to 62,591,637, reverse strand). Ensembl gene ENSG00000149016.
Subcellular location: Nucleus, nucleolus; Nucleus speckle
Subcellular location (Human Protein Atlas): Nucleoplasm; Cytosol
Pathways (Reactome):
Metabolism of RNA: mRNA Polyadenylation
Gene Ontology:
Molecular function: enzyme binding; enzyme-substrate adaptor activity; mRNA 3'-UTR binding; poly(A) RNA polymerase activity; protein binding; RNA binding; RNA uridylyltransferase activity; U6 snRNA binding; nucleic acid binding
Biological process: co-transcriptional mRNA 3'-end processing, cleavage and polyadenylation pathway; histone mRNA catabolic process; mRNA 3'-end processing; regulation of RNA metabolic process; snRNA processing; U6 snRNA 3'-end processing; polyuridylation-dependent mRNA catabolic process; RNA 3'-end processing
Cellular component: mRNA cleavage and polyadenylation specificity factor complex; nuclear speck; nucleolus; nucleoplasm
Genetic constraint (gnomAD): Loss-of-function variants: 30 observed, 51.1 expected, observed/expected ratio (o/e) 0.59, 90% interval 0.44 to 0.8. The upper end of that interval is the gene's LOEUF score, 0.8, which puts it in group 3 of 6, group 1 being the genes least tolerant of losing a copy. Missense variants: 1,065 observed, 1,160 expected, observed/expected ratio (o/e) 0.92, 90% interval 0.87 to 0.97. Synonymous variants: 470 observed, 482.02 expected, observed/expected ratio (o/e) 0.98, 90% interval 0.9 to 1.05.
Homologues: Orthologues: chimpanzee TUT1 (99% identical), macaque TUT1 (95% identical), pig TUT1 (89% identical), rabbit TUT1 (89% identical), dog TUT1 (87% identical), mouse Tut1 (78% identical), rat Eef1g (78% identical), guinea pig TUT1 (76% identical), tropical clawed frog tut1 (37% identical), zebrafish tut1 (34% identical), Caenorhabditis elegans cid-1 (15% identical), Caenorhabditis elegans gld-2 (12% identical), and 5 more. Paralogues in human: MTPAP (17% identical), TUT4 (16% identical), TUT7 (16% identical), TENT2 (11% identical).
Diseases named in the same sentence as TUT1 in open-access papers:
TUT1 is named in the same sentence as 12 diseases in open-access papers, as found by Europe PMC text mining. Sharing a sentence is not in itself a finding about the gene and the disease. The quoted sentences say what the papers report.
leukemia (1 paper, 2026). A malignant (clonal) hematologic disorder, involving hematopoietic stem cells and characterized by the presence of primitive or atypical myeloid or lymphoid cells in the bone marrow and the blood. "Furthermore, our results also suggest that in leukemia cells, TENT4A, TENT5A, TENT5B, TENT5C, TENT5D, and TUT1 may mediate the non-templated nucleotide additions to the 3'ends of miRNAs." (PMID 42038404, 2026).
neuroblastoma (1 paper, 2021). Neuroblastoma (NB) is the most common solid, extracranial childhood tumor. "There may be a role for TUT1 in the development of neuroblastoma, and the transcription factor EN1 may also be regulated in relation to the predicted target gene TUT1." (PMID 34992653, 2021).
tumor (6 papers, 2013 to 2022). "In osteosarcoma, TUT1, which has been found to be down-regulated, has been reported to affect lipogenesis (via miR-24 and miR-29 and their targets PPARgamma and SREBP-1c) and therefore acts as a tumor suppressor." (PMID 33430133, 2021). "Likewise, the TUT1 down-regulation in breast cancer negatively influences the stability of the pro-apoptotic factor BCL-2-interacting-killer (BIK), also acting as a tumor suppressor." (PMID 33430133, 2021).
infection (2 papers, 2015 to 2023). The state of being infected such as from the introduction of a foreign agent such as serum, vaccine, antigenic substance or organism. "RT-qPCR and WB results confirmed that T. marneffei up-regulated the expression of TUT1 in THP-1 macrophages at 24 h post-infection." (PMID 37845378, 2023). "As a result, more T. marneffei were detected in TUT1-overexpressing THP-1 macrophages at 24 h post-infection, and pro-inflammatory factors (TNF-α, IL-1β) were down-regulated at 24 h post-infection." (PMID 37845378, 2023). "Moreover, at 24 h post infection, the expression of NCOR2-013 isoforms was significantly increased in the T. marneffei-infected TUT1-overexpressing THP-1 macrophages, but significantly decreased in the T. marneffei-infected TUT1-knockdown THP-1 macrophages." (PMID 37845378, 2023). "To determine whether the effect on NCOR2 AS was mediated by direct binding of TUT1, we performed RIP assay in T. marneffei-infected TUT1-overexpressing THP-1 macrophages at 24 h post-infection, and found that TUT1 binds to NCOR2 pre-mRNA." (PMID 37845378, 2023).
TUT1 also shares sentences with these, for which no sentence is quoted: breast carcinoma (4 papers); cancer (4); osteosarcoma (2); African Trypanosomiasis (1); bone cancer (1); breast tumors (1); head and neck carcinoma (1); ovarian carcinoma (1).